ALB (albumin)
Diseases named in the same sentence as ALB in open-access papers (continued):
Sharing a sentence is not in itself a finding about the gene and the disease.
ischemic stroke (continued). "At baseline, a total of 182 consecutive participants with HT and 182 age- and sex-matched ischemic stroke patients without HT were enrolled in this study, among whom 345 (94.8%) patients had information on all the lymphocyte count, total cholesterol, and albumin data." (PMID 36276820, 2022). "Interestingly, total urinary albumin/creatinine and nonimmunoreactive albumin/creatinine ratios showed a good correlation with urinary o-Tyr/creatinine ratio in patients suffering from ischemic stroke in our other study." (PMID 26576228, 2015).
Hepatitis (115 papers, 2007 to 2025). Inflammation of the liver. "As per the current study findings, a significant association of hepatitis was observed with age, residence, symptomatic, total bilirubin level, direct bilirubin level, and albumin level." (PMID 35785014, 2022). "The combination of serum levels of GP73, AST and ALB establish a diagnostic model that significantly improved the diagnostic performance for liver inflammation in patients with normal or slightly raised serum ALT." (PMID 30718535, 2019). "In this regard, hepatitis and liver damage, associated with a marked immune infiltration, elevated serum alanine aminotransferase and diminished albumin in Treg cell-depleted Foxp3DTR mice, were undetectable in Foxp3AIDR26TIR1(F74G) mice after 4 weeks of continuous Foxp3 degradation." (PMID 41062655, 2025). "A significant association of hepatitis was observed with age (p-value < 0.001), residence (p-value = 0.048), symptomatic (p-value < 0.001), total bilirubin level (p-value = 0.003), direct bilirubin level (p-value = 0.002), and albumin level (p-value = 0.003)." (PMID 35785014, 2022). "Type of tuberculosis, Severity of tuberculosis diagnosis, taking other hepatotoxic drugs, having preexisting chronic liver disease, HIV infection, lower serum albumin level, and abnormal baseline liver enzymes were significantly associated with the development of drug-induced hepatitis." (PMID 33170847, 2020). "In contrast, incubation with serum albumin before administration greatly enhances the gene expression in the lungs, liver, and spleen of hepatitis mice." (PMID 38675183, 2024). "Early observations of the transmission of hepatitis by pooled plasma and serum led to the incorporation of heat treatment of the albumin solution produced by industrial Cohn fractionation of plasma." (PMID 36839590, 2023). "For both hypothyroidism and hepatitis, the percentages remained relatively consistent across albumin levels in both the APD and CAPD groups, with p-values indicating no statistical significance." (PMID 38021540, 2023). "Most HCC patients have a background of hepatitis, and the presence of an inflammatory response can reduce serum albumin levels." (PMID 36675418, 2023). "As Atp7b−/− rats shortly die upon hepatitis onset, we thus switched to cellular studies here to investigate potential toxicity to such copper pulses, that is, loosely albumin-bound copper." (PMID 34857647, 2022). "Albumin was often used by clinicians to assess a patient’s nutritional status, low albumin levels indicated possible disease, including nephritis, hepatitis, cancer, and other infectious diseases (Rozga, Piątek & Małkowski, 2013)." (PMID 36540802, 2022). "Influence of hepatitis activity on Albumin platelet product was evaluated based on HCV-specific patients in the training cohort." (PMID 33674669, 2021). "In the liver, the interaction with albumin enhanced gene expression in hepatitis mice, while in the lung, the interaction with serum or albumin enhanced it." (PMID 32290201, 2020). "Actually, the synthesis of plasma proteins, such as albumin, fibrinogen, and gamma globulin, was decreased in CCl4-induced hepatitis rat." (PMID 32290201, 2020). "We found that hepatic and pulmonary gene expressions after i.v. injection of lipoplex interacted with albumin were enhanced in CCl4-induced hepatitis mice." (PMID 32290201, 2020). "Having preexisting chronic liver disease, taking other hepatotoxic drugs and lower serum albumin were found to be independent predictors of developing drug-induced hepatitis." (PMID 33170847, 2020). "We suggest that the interaction with albumin enhanced the inflammation level after the administration of lipoplex in hepatitis mice." (PMID 32290201, 2020). "Laboratory work up for other causes of blood dyscrasias included negative screenings for chronic infections [human immunodeficiency virus (HIV) and hepatitis], normal serum levels of albumin, vitamin B12 and folate." (PMID 32448188, 2020).
Hepatitis (continued). "Lower serum albumin, taking other hepatotoxic drugs, and having preexisting chronic liver disease were found to be independent predictors of drug-induced hepatitis." (PMID 33170847, 2020). "In this study, the interaction with albumin increased the serum AST activity level after i.v. injection in hepatitis mice." (PMID 32290201, 2020). "This suggests that antiviral therapy influences the expected capacity of the CRP/ALB ratio, which should be confirmed in future studies investigating the dose and timing of antiviral therapy in other types of hepatitis." (PMID 31821367, 2019). "Various biomarkers of liver function, including the serum bilirubin, ALT, AST, and ALB concentrations, correlate with the findings of T2* magnetic resonance imaging (MRI), a technique used to evaluate the severity of hepatic iron overload." (PMID 31646984, 2019). "We found that, in the early stages of NAFLD and hepatitis, there were already various extents of damage to albumin's fatty acid binding capacity, in which hepatitis patients suffered more severe damages." (PMID 28101103, 2016). "Both NAFLD and hepatitis patients showed significantly decreased TBS/albumin values compared to that of the healthy volunteers (P < 0.001)." (PMID 28101103, 2016). "In our study, the expression level of miR-122 had a significant positive correlation with the grade of liver inflammation, serum albumin value, or serum HCVRNA value." (PMID 23152743, 2012). "Other liver function tests like low levels of serum albumin also reflect high grades of liver inflammation." (PMID 22697612, 2012). "Blood test results for bilirubin, alanine aminotransferase, alkaline phosphatase, and albumin were available for 10 of 11 participants with symptomatic hepatitis." (PMID 19891860, 2009). "Our patient had a low serum albumin (2.6 gm %), however this has been seen in an earlier study involving patients with dengue who had evidence of hepatitis." (PMID 18831758, 2008). "In this regard, hepatitis and liver damage, associated with a marked immune infiltration, elevated serum alanine aminotransferase (ALT) and diminished albumin in Treg-depleted Foxp3DTR mice, were undetectable in Foxp3AIDR26TIR1(F74G) mice after four weeks of continuous Foxp3 degradation." (PMID 40470210, 2025). "Similarly, hepatitis B virus (HBV) infection has been associated with elevated levels of glucose and albumin." (PMID 40284260, 2025). "However, hepatitis E patients had significantly lower serum albumin levels than hepatitis A patients." (PMID 37766294, 2023). "As eight patients had hepatitis and displayed a decrease in ALB and CHE and an increase in ALT and TBIL, which might lead to bias in our results, these patients were excluded and a re-analysis was performed." (PMID 35756643, 2022). "In hepatitis mice, interaction with albumin significantly contributes to gene expression." (PMID 33530309, 2021). "However, the prognostic performance of serum albumin level, either alone or combined with hepatitis B viral factors, for HBV-related HCC recurrence remains poorly explored." (PMID 34575311, 2021). "In addition, the role of albumin interaction with lipoplexes is different in healthy and hepatitis mice, and sonoporation effectively transfers plasmid DNA in peritoneal fibrotic site, while linear PEI fails to transfer." (PMID 33530309, 2021). "This suggests that enhanced hepatic accumulation of lipoplex interacted with albumin might be attributed to lower pH in the liver of hepatitis mice than that in normal mice." (PMID 32290201, 2020). "Furthermore, hepatic and pulmonary gene expression levels of albumin-interacted lipoplex were correlated with serum transaminases in hepatitis mice." (PMID 32290201, 2020).
Hepatitis (continued). "Logistic regression analysis revealed that ALB (P = 0.010), cholinesterase (CHE) (P = 0.000), and APRI (P = 0.005) were predictive indices of the risk of liver inflammation, with an OR of 0.82 (95% CI: 0.70–0.95), 0.99 (95% CI: 0.99–1.00), and 4.16 (95% CI: 1.55–11.18), respectively." (PMID 26236336, 2015). "ALT, which is particularly sensitive to storage at −20°C, was elevated in a large fraction of patients with acute hepatitis A and B. Albumin was specifically decreased (relative to total protein) in most patients, while total bilirubin was elevated in particular in patients with acute hepatitis." (PMID 24069490, 2013). "Among these tools, the reason for the poor consistency between NRI and the other three tools may be that many in-patients with cystic echinococcosis also have other diseases such as hepatitis, infections, etc., which lead to decreases in albumin and affect the NRI score." (PMID 33357363, 2020). "Therefore, the microbiota might affect the synthesis of liver ALB through the linoleic acid metabolism of the host, thereby decreasing serum ALB levels and hepatitis." (PMID 31073525, 2019). "In this study, we identified Age, AST, PT, ALB and HBV DNA as independent predictors of significant liver inflammation in IT-phase patients." (PMID 39856182, 2025). "As a direct index reflecting hepatitis, we found that hepatitis had a close relationship with elevated serum ALT levels and decreased PLT and ALB levels." (PMID 38622578, 2024). "Multivariable Cox regression analysis was performed, including group, age, hepatitis, AFP, ALB, TB, ALBI grade, ascites, maximum tumor size, tumor number, BCLC stage, and Child-Pugh grade." (PMID 38380330, 2024). "Basic laboratory studies such as vitamin B12, folate, albumin, ANA, HIV screening, hepatitis panel should be obtained upon initial evaluation." (PMID 32448188, 2020). "When ROC analysis was performed on Model1 consisting of combined GP73, ALB and AST for prediction of significant liver inflammation, a cut off value of 5.31 was identified." (PMID 30718535, 2019). "Model1 consisted of a combination of GP73, ALB and AST, which significantly improved the detection of liver inflammation in patients with normal or slightly raised serum ALT, compared to GP73 alone (AUC value increased from 0.806 to 0.854, p < 0.05)." (PMID 30718535, 2019). "Our results showed that albumin conformation was damaged in NAFLD and hepatitis patients, while the damage was more severe in hepatitis patients." (PMID 28101103, 2016). "Our results showed that TBS/albumin value decreased significantly in NAFLD and hepatitis patients over the healthy volunteers (P < 0.01)." (PMID 28101103, 2016). "In comparison of liver functions, our EHPM patients have better liver functions reserve such as higher rates in Child-Pugh class A and higher albumin levels, and lower AST and ALT levels that reflected less hepatitis activity." (PMID 27444261, 2016). "ARFI elastography was properly correlated with biochemical markers for hepatitis as it was directly correlated to AST; ALT; INR while it was inversely correlated to albumin; prothrombin concentration and platelets." (PMID 27703558, 2016). "The biochemical markers AST, ALT, TP, ALB and LDH are widely used to diagnose many types of human hepatitis." (PMID 26731101, 2016). "Therefore, we established and validated a non-invasive predictive nomogram model based on five serological markers (Age, AST, PT, ALB and HBV DNA) to facilitate the early identification of significant liver inflammation in the IT phase." (PMID 39856182, 2025). "Serum DCP in HCC patients positively correlated with gender, tumor size, tumor number, vascular invasion, hepatitis, AFP, ALT, AST, total bilirubin, direct bilirubin, indirect bilirubin, albumin, and A/G ratio (p < 0.05), but negatively correlated with age (p < 0.05)." (PMID 40230049, 2025).
Hepatitis (continued). "Following decades of demonstrated safety by pasteurised albumin, early efforts focussed on enhancing the safety of Factor VIII concentrate from hepatitis transmission using this method, with the additional feature of adding excipients to protect factor VIII from inactivation." (PMID 36839590, 2023). "Albumin not subjected to this pasteurisation step transmitted hepatitis, showing that the fractionation alone does not eliminate the risk." (PMID 36839590, 2023). "The absence of transmission of hepatitis, or any subsequently emergent blood-borne agent, by albumin fractionated by the Cohn method, has been ascribed to the heat treatment step introduced early on its use." (PMID 36839590, 2023). "Potential precipitating events of ACLF are bacterial infections, gastrointestinal hemorrhage, active alcoholism, transjugular intrahepatic portosystemic shunting, therapeutic paracentesis without the use of intravenous albumin, hepatitis, and major surgery." (PMID 36676081, 2023). "This led to an absence of pathogen transmission by albumin over decades, during which hepatitis continued to be transmitted by other early plasma fractions, as well as through mainstream blood transfusions." (PMID 36839590, 2023). "Mice expressing IL22 under an albumin promoter do not develop liver inflammation but are resistant to ConA T cell-mediated hepatitis." (PMID 33452360, 2021). "Rats administered fluvastatin (hepatitis group) showed significantly (p < 0.05) higher levels of liver damage parameters (AST, ALT, ALP, γ-GTP, and total bilirubin) and significantly lower levels of albumin than the control group." (PMID 34344946, 2021). "They did not have significantly higher MELD or FIB-4 scores at baseline, but they were more likely than other patients to have labs suggestive of liver inflammation and dysfunction, such as elevated ALT, low platelets, elevated bilirubin, elevated INR and low albumin." (PMID 31797589, 2020). "Finally, neither PC3X, PRO-C5 nor PRO-C6 correlate with parameters of liver inflammation and parameters of liver function, such as albumin, ALT, AST, cholinesterase, and platelet count when calculated in a Spearmans correlation analysis." (PMID 36694115, 2023). "This pattern may indicate hepatocellular injury (hepatitis); however, the low albumin level can be attributed to its being a negative acute-phase reactant, and the improvement occurred after the resolution of the liver injury." (PMID 31623668, 2019). "Suppression of hepatitis by DAA treatment may reduce inflammatory cytokines and preserve ASGPR function, thereby restoring the differentiation and proliferation potential of residual hepatocytes and improving the ability to synthesize albumin, prothrombin, and other substances." (PMID 36729172, 2023). "Twenty-one patients with liver inflammation (ALT more than 2 ULN) were allocated into group A. Thirty-four patients without liver inflammation (ALT less than 2 ULN) were allocated into group B. Age, sex, and ALB did not markedly vary between the two groups." (PMID 39927273, 2024). "In none of the patients, mild hepatitis was accompanied by the impairment of liver function; however, AST, but not ALT, tended to be negatively correlated with albumin levels at admission and during Tx." (PMID 33572429, 2021). "Our analysis showed that admission CK was not helpful in identifying severe dengue and does not correlate with any of the biomarkers which represent hepatitis (ALT), plasma leakage (hematocrit and serum albumin) and disease course (platelet count)." (PMID 28732476, 2017). "We do not deny the idea that cessation of hepatitis, which is represented by lowering of serum ALT levels, contributed to and increase of serum albumin levels." (PMID 17470300, 2007).
Hepatitis (continued). "The differences in gender, age, AFP, ALB, TB, ALBI grade, maximum tumor size, tumor number, hepatitis, ascites, Child–Pugh grade, and BCLC stage were not statistically significant (P>0.05), indicating a balanced baseline and comparability between the two groups." (PMID 38380330, 2024). "In MHV-induced hepatitis, the plasma free Trp may be upregulated, which is supported by evidence of decreasing albumin and increasing non-esterified fatty acids (NEFA) in hepatitis patients." (PMID 34869457, 2021).